PFKFB3 (6-phosphofructo-2-kinase/fructose-2,6-biphosphatase 3)
Diseases named in the same sentence as PFKFB3 in open-access papers (continued):
Sharing a sentence is not in itself a finding about the gene and the disease.
renal fibrosis (continued). "In conclusion, our study provides compelling evidence that PFKFB3 plays a crucial role in the development of renal fibrosis." (PMID 37626891, 2023). "In addition, IRF3 drives hypoxia-induced renal fibrosis via upregulation of PFKFB3-dependent glycolysis." (PMID 41208891, 2025). "Additionally, studies report that HIF-1α mediates myeloid macrophage polarization via PFKFB3 and promotes renal fibrosis." (PMID 41375167, 2025). "Thus, the Mettl3/Pfkfb3/lactate/ H3K18la/PD-L1 axis regulates renal fibrosis induced by low-dose cisplatin." (PMID 40765834, 2025). "In CKD, the PFKFB3-H4K12la-NF-κB axis drives renal fibrosis progression." (PMID 40881348, 2025). "We then try to further understand how Pfkfb3 participates in the process of renal fibrosis." (PMID 40765834, 2025). "Inhibition of PFKFB3 in vitro resulted in the suppression of fibroblast activation and proliferation, while myofibroblast-specific knockout of Pfkfb3 significantly inhibited renal fibrosis induced by UUO and kidney ischemia/reperfusion in vivo." (PMID 37626891, 2023). "Moreover, the interstitial collagen deposition (Masson’s trichrome staining, Sirius Red staining, and immunostaining of collagen I and collagen IV) also indicated significant suppression of renal fibrosis by myofibroblast Pfkfb3 knockout." (PMID 37626891, 2023). "Therefore, in the context of renal fibrosis, PFKFB3 primarily regulates fibroblast activation through the promotion of glycolysis." (PMID 37626891, 2023). "However, the effect of glycolysis on macrophage differentiation and the significance of myeloid PFKFB3-mediated glycolysis in the development of renal fibrosis has yet to be fully elucidated." (PMID 38035106, 2023). "In addition, we confirmed the novel role of PFKFB3 in renal fibrosis through the regulation of glycolysis." (PMID 37626891, 2023). "PLGA-encapsulated Levosimendan not only alleviates repeated low-dose CDDP-induced renal fibrosis, but also significantly enhances the chemotherapeutic effects of cisplatin in several xenograft and syngeneic mouse tumor models by suppressing the Mettl3/Pfkfb3/lactate/ H3K18la/PD-L1 axis." (PMID 40765834, 2025). "However, it remains unclear whether PFKFB3 in renal fibroblasts is crucial for the fibrotic activity of myofibroblasts and subsequent renal fibrosis." (PMID 37626891, 2023). "Yet, 6-phosphofructo-2-kinase/fructose-2,6-bisphosphatase 3 (PFKFB3), an essential glycolytic activator in renal fibrosis, is little understood." (PMID 40271532, 2025). "•Liver cirrhosis alters glycolysis via LDH, PDHE1α, HIF1α, PFKFB3 and GLUT1/2 contributing to renal fibrosis." (PMID 40271532, 2025). "A significant body of studies has confirmed the pivotal role of glycolysis in CKD pathogenesis, revealing a positive correlation between elevated levels of glycolysis enzymes (PFKFB3, PKM2) and renal fibrosis degree, as well as Cr and BUN levels in CKD patients." (PMID 39457592, 2024). "Our study also implicates that PFKFB3 may act as a bridge to mediate the crosstalk of TGF-β1 and HIF-1α signaling pathways in renal fibrosis." (PMID 38035106, 2023).
glioma (10 papers, 2013 to 2023). A benign or malignant brain and spinal cord tumor that arises from glial cells (astrocytes, oligodendrocytes, ependymal cells). "In contrast, the PFKFB3 gene, in particular the i-PFK2 splice variant, has been recently shown to be a target for loss of heterozygosity on 10p14-p15, which is common in high-grade gliomas." (PMID 24280138, 2013). "In brain tumors, including high-grade gliomas, PFKFB3 expression has been linked to poor survival." (PMID 34831136, 2021). "It has been documented that TGFβ1 induced the overexpression of PFKFB3 in glioma cells, leading to a glycolytic flux with an increase in the glucose uptake and lactate production." (PMID 38139462, 2023). "Inhibitors directed to PFKFB3, such as 3PO, have also been proven in glioma models." (PMID 38139462, 2023). "In addition to its glycolytic activities, PFKFB3 also plays an important role in numerous human tumors, including lung, breast, colon, pancreas, ovary, gastric, and glioma tumors." (PMID 33931981, 2021). "Moreover, PFKFB3 induction by TGF-β1 has been shown to be a key regulator of glioma reprogramming and colony formation." (PMID 34831136, 2021). "Overly expressed PFKFB3 in gliomas may be due to their cellular origin." (PMID 34831136, 2021). "PFKFB3 protein levels are significantly higher in high-grade glioma than in non-pathologic brain tissue or lower grade gliomas, but without relative upregulation of transcript levels." (PMID 34831136, 2021). "Tumor glycolytic enzymes hexokinase 2 (HK2), 6-phosphofructo-2-kinase/fructose-2,6-bisphosphatase (PFKFB3), pyruvate kinase M2 (PKM2), and lactate dehydrogenase 5 (LDH5) demonstrate increased activity in the glioma cells and supposed to be preferentially used by cancer cells." (PMID 34440090, 2021). "PFKFB3 protein levels are significantly higher in HGGs than in non-pathologic brain tissue or lower grade gliomas, but without a relative upregulation of transcript levels." (PMID 34831136, 2021). "Thus, the levels of the PFKFB3 gene are significantly higher in high-grade gliomas (G3 and G4 degrees of differentiation) than in non-pathological brain tissues or gliomas with G1 and G2 degrees of differentiation." (PMID 37834214, 2023).
leukemia (10 papers, 2013 to 2024). A malignant (clonal) hematologic disorder, involving hematopoietic stem cells and characterized by the presence of primitive or atypical myeloid or lymphoid cells in the bone marrow and the blood. "Overexpression of PFKFB3 promotes glucose uptake and cell proliferation, whereas downregulation of PFKFB3 strongly suppresses leukemia growth both in vitro and in vivo." (PMID 36768405, 2023). "High expression of PFKFB3 was observed in various types of cancer including colon, prostate, lung, breast, pancreas, thyroid, and ovarian tumors as well as in leukemias." (PMID 26337471, 2015). "The Pfkfb3 gene was first cloned from fetal brain cDNA libraries, and PFKFB3 protein is widely expressed in all tissues, especially in proliferating tissues, transformed cells, solid tumors and leukemia cells." (PMID 39318551, 2024). "On the one hand, TIGAR inhibited glycolysis through PFKFB3 in leukemia cells." (PMID 27884166, 2016). "Indeed, PFKFB3 is induced by a myriad of mitogenic, inflammatory, and hypoxic stimuli and is constitutively expressed in a number of leukemias and solid tumors." (PMID 24204309, 2013). "TIGAR also showed high expression in multiple human leukemia cell lines and knockdown of TIGAR activated glycolysis through PFKFB3 upregulation in human leukemia cells." (PMID 27884166, 2016). "However, crosstalk between these genes must exist in cancer cells since it has been observed that when TIGAR is eliminated in leukemia cells expressing high levels of TIGAR, PFKFB3 expression increase, and when TIGAR is overexpressed in cells with low levels of TIGAR, PFKFB3 expression decrease." (PMID 30234009, 2018).
nasopharyngeal carcinoma (10 papers, 2020 to 2025). A carcinoma arising from the nasopharyngeal epithelium. "Furthermore, in nasopharyngeal carcinoma and oral squamous cell carcinoma, PFKFB3 is crucial for metastasis." (PMID 33803236, 2021). "Moreover, a recent study suggested that PFKFB3 may be a novel epithelial-mesenchymal transition inducer and regulates the invasion and migration in nasopharyngeal carcinoma progression." (PMID 37253634, 2023). "PFKFB3 knockdown inhibits invasiveness by upregulating E-cadherin and downregulating vimentin and N-cadherin levels in CNE2 human nasopharyngeal carcinoma cells." (PMID 37919747, 2023). "It promoted glycolytic flux and cell cycle progression in nasopharyngeal cancer by increasing H3K4 trimethylation and H3K9 acetylation levels in the PFKFB3 promoter region, which epigenetically transactivates PFKFB3." (PMID 36639695, 2023). "We are actively pursuing a clinical strategy to treat nasopharyngeal carcinoma by interfering with LINC00930 and the target gene PFKFB3." (PMID 35209949, 2022). "LINC00930 was first reported in nasopharyngeal carcinoma, where it binds the RBBP5 and GCN5 complexes to the PFKFB3 promoter, elevates H3K4 trimethylation and H3K9 acetylation levels, transactivating PFKFB3, thereby promoting glycolytic flux and cell cycle progression." (PMID 38789960, 2024). "For example, LINC00930, an oncogenic lncRNA in nasopharyngeal carcinoma, promoted PFKFB3‐mediated glycolysis and histone modification, and targeting LINC00930 and PFKFB3 may be an effective approach to enhance radiosensitivity in patients with nasopharyngeal carcinoma." (PMID 35924724, 2023).
pulmonary hypertension (10 papers, 2020 to 2025). Increased pressure within the pulmonary circulation due to lung or heart disorder. "Upregulated PFKFB3 reportedly mediates collagen synthesis and proliferation of pulmonary artery SMCs, contributing to vascular remodeling in pulmonary arterial hypertension." (PMID 34016793, 2021). "Through murine studies PFKFB3 has been identified as potential therapeutic target for the treatment of Pulmonary Hypertension (PH)." (PMID 33552042, 2020). "PFKFB3-mediated glycolysis in endothelial cells is critical in angiogenesis and the development of inflammatory diseases, such as retinopathy, pulmonary hypertension, and metastatic cancers." (PMID 39318551, 2024). "Notably, genetic or pharmacologic inactivation of PFKFB3 abrogated inflammation in various disease models such as and LPS and pulmonary hypertension, linking PFKFB3-driven glycolysis to endothelial proinflammatory pathways." (PMID 39621585, 2024). "Interestingly, studies on the role of endothelially expressed Pfkfb3 suggest that inducible deletion of Pfkfb3 is protective during pulmonary hypertension or during LPS-induced ALI." (PMID 36326834, 2022).
Hyperglycemia (9 papers, 2012 to 2025). An increased concentration of glucose in the blood. "TargetScan and OncomiR were utilized to explore the potential mechanism of PFKFB3 overexpression by hyperglycemia." (PMID 36973739, 2023). "TargetScan database was utilized to explore the potential mechanism of PFKFB3 overexpression by hyperglycemia." (PMID 36973739, 2023). "In view of microRNA’s negative regulation of its target gene expression, we aimed to confirm that PFKFB3 down-regulated by miR-26-5p inhibited the proliferation and metastasis of GC induced by hyperglycemia." (PMID 35094634, 2022). "This was consistent with the results of our study: hyperglycemia promoted EMT through PFKFB3 overexpression." (PMID 35094634, 2022). "Our study mainly focused on the effects of PFKFB3 overexpression induced by hyperglycemia on GC progression and its mechanism." (PMID 35094634, 2022). "Metabolic disruption also extends to thrombotic mechanisms: platelet activation requires a glycolytic ATP surge mediated by HK2 and 6-phosphofructo-2-kinase/fructose-2,6-biphosphatase 3 (PFKFB3), while hyperglycemia stiffens clots via advanced glycation end-product (AGE) crosslinking." (PMID 41184254, 2025). "An increase in miR-26 expression can inhibit the hyperglycemia-induced overexpression of PFKFB3." (PMID 40001538, 2025). "However, as the weeks progressed, body weight and hyperglycemia in ob/ob mice increased and higher PFKFB3 expression was observed." (PMID 40600018, 2025). "Therefore, PFKFB3 down-regulated by miR-26-5p inhibited the malignant phenotype of GC with hyperglycemia." (PMID 35094634, 2022). "In general, we hypothesized that hyperglycemia induced the down-regulation of miR-26 to overexpress PFKFB3 and promote the malignant phenotype of GC cells." (PMID 35094634, 2022). "Hyperglycaemia-induced upregulation of several glycolytic genes was reduced by S6K inhibition, including aldolase B, Pdk1 and 6-phosphofructo-2-kinase/fructose-2,6-biphosphatase 3 (Pfkfb3), a bifunctional enzyme that converts F6P to F2,6BP, a potent activator of phosphofructokinase." (PMID 36376280, 2022). "Besides, hyperglycemia upregulated PFKFB3 expression via inhibiting the expression level of miR-26-5p, which promoted the proliferation, migration and EMT through the TGF-β/Smad signaling pathway in GC." (PMID 35094634, 2022). "Therefore, the upregulation of PFKFB3 attributed to the miR-26 downregulation induced by hyperglycemia." (PMID 35094634, 2022). "In short, miR-26-5p inhibited PFKFB3 upregulation induced by hyperglycemia." (PMID 35094634, 2022). "Besides, hyperglycemia stimulated the higher expression of PFKFB3 along with the enhanced proliferation, migration and epithelial–mesenchymal transition (EMT) in GC cells." (PMID 35094634, 2022). "To assure that this pathway was activated well before any confounding effects of hyperglycemia, we evaluated islets from HIP rats at 2.5 and 3.5 months of age, and found that PFKFB3 levels were already increased by 2.5 months of age, namely before frank hyperglycemia." (PMID 31213603, 2019). "Therefore, we proposed a hypothesis that PFKFB3 expression can be upregulated with increasing glucose concentration and contributes to the poor prognosis of GC patients with hyperglycemia." (PMID 35094634, 2022). "The results indicated that downregulation of miR-26-5p induced by hyperglycemia promoted GC cells proliferation, migration and EMT via PFKFB3 overexpression." (PMID 35094634, 2022). "However, the role of PFKFB3 in GC patients with hyperglycemia remains unclear." (PMID 35094634, 2022). "At 6 weeks of age, when hyperglycemia was not pronounced, PFKFB3 expression in pancreatic beta cells of ob/ob mice was not clearly different from that of control ob/+ mice." (PMID 40600018, 2025).
Insulin resistance (8 papers, 2014 to 2025). Increased resistance towards insulin, that is, diminished effectiveness of insulin in reducing blood glucose levels. "Based on this relationship, it is likely that PFKFB3/iPFK2 in IECs participates in the regulation of obesity-associated insulin resistance and dysregulation of glucose homeostasis." (PMID 27387960, 2016). "In contrast, an earlier study reported that transgenic mice with reduced PFKFB3 expression show exacerbated diet-induced insulin resistance." (PMID 31888951, 2020). "It should be pointed out that the HFD-induced decrease in PFKFB3/iPFK2 expression in the primary IECs was reversely correlated with systemic insulin resistance." (PMID 27387960, 2016). "To investigate nutritional regulation of IEC PFKFB3/iPFK2 expression and inflammatory responses in the context of obesity and insulin resistance, we fed C57BL/6J mice a HFD for 12 weeks." (PMID 27387960, 2016). "The disruption of PFKFB3 in macrophages could intensify diet-induced inflammation in white adipose tissue and insulin resistance via augmenting NF-κB p65 phosphorylation." (PMID 41425966, 2025). "Finally, expression of 6-phosphofructo-2-kinase/fructose-2,6-biphosphatase 3 (Pfkfb3), a gene shown to be protective from diet-induced insulin resistance when overexpressed in adipose tissue, was significantly increased in the HFD mice with exercise." (PMID 31027261, 2019). "Research has shown that schistosomiasis affected the glucose metabolism of host, leading to the upregulation of glycolysis-related genes in the liver, such as Ldha, Glut4, Pkm2, Glut1, Pfkfb3, Aldoc, HK2, and Pfk and could also improve insulin resistance." (PMID 40152283, 2025). "To avoid systemic effects of Pfkfb3 overexpression we studied cultured L6-GLUT4-HA myotubes, which display robust insulin regulation of GLUT4 trafficking and develop insulin resistance upon palmitate treatment, mimicking lipotoxicity, a trigger of in vivo insulin resistance." (PMID 38329473, 2024).
Obesity (8 papers, 2016 to 2025). Accumulation of substantial excess body fat. "Overall, diet has a significant impact on PFKFB3/iPFK2 expression within IECs in the context of obesity-associated inflammation." (PMID 27387960, 2016). "This would support a hypothesis that polymorphisms leading to a decrease in PFKFB3 expression may be protective from the development of obesity; however, tissue-specific transcriptional studies in humans would be required to fully support this assertion." (PMID 31888951, 2020). "Because of this, activating PFKFB3/iPFK2 in IECs through nutritional approaches could be beneficial for obesity-associated metabolic diseases." (PMID 27387960, 2016). "Disruption of PFKFB3/iPFK2 decreases HFD-induced obesity, but exacerbates adipose tissue inflammation, which contributes to an increase in the severity of IR." (PMID 34943809, 2021). "We also identified SNPs in two genes, PFKFB3 and CABP5, which are associated with obesity in other studies." (PMID 31888951, 2020). "Notably, in contrast to the findings in VAT, a significant decrease of PFKFB3 levels was detected in PBMCs of individuals with obesity compared to the NW controls." (PMID 39256343, 2024). "Elevated expression of PFKFB3 in obesity has been previously reported." (PMID 39256343, 2024). "Thus, pharmacological inhibition of PFKFB3 and appropriate glycemic control may be of therapeutic value in managing obesity-induced endothelial dysfunction." (PMID 40002359, 2025). "Therefore, as PFKFB3 protein is unstable in skeletal muscle, tissue‐specific targeting of PFKFB3 either through protein expression level, protein stability or enzyme activity may represent novel therapeutics for the treatment of metabolic disorders related to obesity." (PMID 34227742, 2021). "Our extreme obesity vs. non-obese study also identified two new genes, PFKFB3 and KLRB1, that are not yet found to be significantly associated to BMI." (PMID 31888951, 2020). "However, a direct link between obesity-induced EC dysfunction and PFKFB3 is not yet established." (PMID 40002359, 2025). "The levels of PFKFB3, the major regulator of glycolysis, showed a significant increase in VAT but not in SAT from patients with obesity versus adipose tissues from NW individuals." (PMID 39256343, 2024).
acute myeloid leukemia (7 papers, 2017 to 2023). Acute myeloid leukemia (AML) is a group of neoplasms arising from precursor cells committed to the myeloid cell-line differentiation. "It promotes the proliferation of acute myeloid leukemia by up-regulating the expression of 6-phosphofructo-2-kinase/fructose-2,6-bisphosphatase (PFKFB3), a key glycolytic regulator." (PMID 37512503, 2023). "Moreover, ROS stimulated the proliferation of acute myeloid leukemia by upregulating glycolytic regulator phosphofructokinase (PFKFB3)." (PMID 36441489, 2023). "Robinson et al23 demonstrated that NOX2 in acute myeloid leukemia (AML) cells can promote glycolysis by activating PFKFB3, thus driving the proliferation of AML cells." (PMID 37860833, 2023). "In acute myeloid leukemia (AML), mTOR-mediated up-regulation of PFKFB3 is essential for cell survival, as mTORC1 up-regulates PFKFB3 in a HIF1α-dependent manner, and PFKFB3 silencing suppresses glycolysis and cell proliferation and activates apoptosis." (PMID 30234009, 2018). "PFKFB3 also plays an important role in the survival of acute myeloid leukemia (AML) cells, as PFKFB3 is a novel downstream substrate of the mTOR (mechanistic target of rapamycin) signaling pathway." (PMID 28977989, 2017). "Further analysis of PFKFB3 expression indicated positive correlations with MSI in acute myeloid leukemia (LAML), LUSC, and COAD; and negative correlations with MSI in PRAD, STAD, and DLBC." (PMID 37253634, 2023).